CXCR6 (C-X-C motif chemokine receptor 6)
Diseases named in the same sentence as CXCR6 in open-access papers (continued):
Sharing a sentence is not in itself a finding about the gene and the disease.
tumor (continued). "Consistent expression of CXCR3 on both subsets and selective late expression of CXCR6 on resident memory cells suggest that while CXCR3 may direct default peripheral migration of both memory subsets to the tumor, CXCR6 selectively promotes tissue residency of memory cells." (PMID 34607898, 2021). "This suggests that CXCR6 may serve as a retention signal to keep TRM precursors in the tumor." (PMID 33979626, 2021). "However, our scRNA-seq and FACS data demonstrated a strong correlation between CXCR6 and PD-1 expression, which suggests that it could be related to tumor antigen stimulation." (PMID 33979626, 2021). "It has been reported that CXCR6 could promote tumor metastasis through EMT." (PMID 33549109, 2021). "In addition, expression of CXCL16 inversely correlated with tumor stage, the invasion depth of the tumor and lymphatic invasion, what may suggest that this chemokine and its receptor CXCR6 may play a role in gastric tumorigenesis." (PMID 33182840, 2020). "Hence, MAIT cells may persistently express CCR6 and CXCR6 when they migrate into the tumor environment." (PMID 26837580, 2016). "Therefore, although CXCR6/CXCL16 interactions enhance beneficial IFNγ responses from iNKT cells, there could be additional mediators or processes regulated by CXCR6/CXCL16 interactions that contribute to tumor control." (PMID 27471636, 2016). "Together our data suggest that CXCL16 and CXCR6 may contribute to tumor progression directly through effects on cancer cell growth, and indirectly, by enhancing leukocyte recruitment and proliferation and the interactions between leukocytes and pre-malignant/malignant cells." (PMID 19690611, 2009). "Within the tumor microenvironment, gene expression profiling revealed upregulated chemokine signaling pathways (CCR2/CCL7, CXCR6/CXCL16) and key immunosuppressive markers, including PD-L1 and TGF-β1." (PMID 42227811, 2026). "Microbial bile-acid derivatives tune the hepatic CXCL16-CXCR6 circuit, promoting the recruitment and function of CXCR6+ NKT cells and, in turn, shaping liver-selective tumor immunosurveillance." (PMID 41486167, 2026). "The development of intratumoral bystander TRM cells required intrinsic TGFβ-signaling, and their efficient tumor entry was dependent on CXCR3 and CXCR6 expression." (PMID 41461987, 2026). "Some studies have shown that tumor cells can secrete CXCL16 to recruit immune cells expressing CXCR6, such as NK cells and CD8+ T cells, to the tumor site, which can directly kill tumor cells." (PMID 40539058, 2025). "Co-expression of CCR5, CXCR6, and CXCR3 provides a functional ‘code’ that separates T-cell-mediated anti-tumor efficacy from off-target toxicity, enabling the selection of superior cells for safer and more effective cancer immunotherapies." (PMID 41415437, 2025). "Our findings illustrate that lrNK cells, characterized by CXCR6 and CD69 expression, are more abundant in non-tumor areas during eHCC but decline with disease progression, consistent with previous reports." (PMID 40547009, 2025). "Upregulated expression of CXCR6 enhanced the ability of MSLN-CAR-T cells to migrate and infiltrate from the periphery into tumor tissues." (PMID 40148310, 2025). "In our current study, we have demonstrated through various approaches that GC tumor cells highly express CXCL16, while Tc17 cells, a subset of T cells, highly express CXCR6." (PMID 40452847, 2025). "The level of CDCA has been reported to correlate with liver sinusoidal endothelial cell CXCL16 mRNA expression, which can promote CXCR6 + hepatic nature killer T (NKT) cell recruitment to the liver and inhibit liver tumor growth in a tumor metastasis model." (PMID 39804065, 2025). "Altogether, these data establish that the functional outcome of P1C4 therapy—tumor rejection versus immune-mediated toxicity—relies on the specific co-expression of CXCR3, CCR5, and CXCR6 on responding T cells." (PMID 41415437, 2025).
tumor (continued). "Their findings confirmed that CXCR3, CXCR2, and CXCR6 are prognostic genes related to AML and its tumor immune microenvironment, offering new insights into AML prevention and treatment." (PMID 40427609, 2025). "Lesch and colleagues found that CAR-T cells that strongly express CXCR6 (its ligand is highly expressed by human and mouse PDAC cells and tumor-infiltrating immune cells) enhance the recognition and efficacy against tumor cells." (PMID 38167055, 2024). "Subsequently, we evaluated the immune states of CXCR6+ and CCR5+ T cells in YM101‐treated tumor tissues using flow cytometry." (PMID 39303165, 2024). "Peripheral tissue-resident memory T cells evidenced by markers such as CD103, CD69 and CXCR6 elicited a robust cellular immunity by recruiting and activating cytotoxic CD8 T cells and NK cells in a PD-L1 blockade treatment tumor mouse model." (PMID 39076974, 2024). "In murine tumor models, Maraviroc combined with YM101 suppressed the accumulation of CCR5+ T cells and increased the CXCR6+ T cell population." (PMID 39303165, 2024). "CXC chemokine receptor 6 (CXCR6), a member of the CXC chemokine family, plays an important role in tumor development." (PMID 39588301, 2024). "In the same line, flow cytometry of T cells confirmed higher expression of CXCR6 on CD8+ T cells relative to CD4+ T cells, in agreement with the observation that CD8+ T cells are especially segregated at the tumor margin in the immune-excluded model." (PMID 38509063, 2024). "Through univariate Cox regression analysis, nine genes, including 3 oncogenes (HTR3C, CRHR2 and AGTR1), 6 tumor suppressor genes (CD8A, CD3E, SERPIND1, CXCR6, BMX and CD247) were proved to be correlated with the overall survival of EC patients." (PMID 38355782, 2024). "CXCR6 + CD8 + T cells are more immunocompetent and can be recruited to the TME to exert cytotoxic effects, leading to tumor cell destruction." (PMID 38698468, 2024). "CXCR6 is highly expressed in tumor-specific CD8+ T cells and enhances CD8+ T-cell retention in tumor nests, which is crucial for persistent and effective immunosurveillance." (PMID 38335302, 2024). "A phase II trial found that H101 can trigger a proliferation burst of CXCR6+ and GZMK+CD8+T cells in malignant ascites, enhancing tumor-specific T cell cytotoxicity." (PMID 39588306, 2024). "The CXCR6+ subset exhibited high levels of the exhaustion marker CD39 along with variable levels of the activation marker CD38, being more prevalent in tumor cells." (PMID 39123475, 2024). "In brief, chemokine signaling is crucial for tumor angiogenesis (CXCR2 and CXCR4), immunosuppression (CXCR3 and CCR2), and tumor progression and metastasis (CCR5 and CXCR6)." (PMID 39456552, 2024). "Re-transfer experiments confirmed that EP2/EP4-deficient TIM-3−(TCF1+) OT-I TILs but not their TIM-3+(TCF1−) descendants possessed the capacity to expand in tumours and were able to give rise to TIM-3+CXCR6+ TILs." (PMID 38658748, 2024). "On the other hand, an important study pointed out that CXCR6, the receptor for CXCL16, plays a key role in CTL-mediated tumor control, and contributes to the survival and local expansion of effector-like CTL in the TME." (PMID 36966334, 2023). "Lastly, the loss of Arid2 promoted the expression of KLRD1 and inhibited TCF1 and TOX expression in the CXCR6+CD44+ cluster, further indicating an increased effector profile of tumor-specific CD8+ T cells following PBAF deletion." (PMID 37330910, 2023). "Our data show that Vγ6+ cells express a phenotype with high degree of similarity to Trm CD8+ T cells through production of CXCR6, ICOS, JAML, and PD-1, whose expression is stable between tumor-free and tumor-bearing mice." (PMID 36480166, 2023). "This chemokine receptor can position CD8+ cytotoxic T lymphocytes (CTL) in perivascular niches in the tumor stroma, which is enriched in DC3 (CCR7+ DC) expressing the ligand of CXCR6, CXCL16." (PMID 37545498, 2023).
tumor (continued). "Expression level analysis indicated that CXCR6 and LTA had higher expression in tumor tissues than normal tissues." (PMID 37593098, 2023). "ILC1 also upregulates CXCR6, CCR5, CXCR3, and CCR1 which can recruit RORγt+ ILC3s to the tumor leading to the inhibition of tumor growth." (PMID 38567059, 2023). "Recently, CD8+ T cells expressing CXCR6 have been identified as highly proliferative and functional tumor-infiltrating CD8+ T cells that promote tumor control." (PMID 37330910, 2023). "CXCR6 regulates the accumulation and persistence of effector CD8+ T cells by supporting their survival in the tumor tissue." (PMID 37545498, 2023). "In primary tumors, PCa-derived CXCL16 recruits CXCR6-expressing MSCs which upregulate PCa CXCR4 expression, induce EMT markers via CXCL12 secretion, and promote tumor growth in vivo in a subcutaneous model." (PMID 37025604, 2023). "In tumour tissues, there were more MSCs in CXCR6+/+ mice than CXCR6−/− mice, suggesting specific recruitment of MSCs into tumours via the CXCL16-CXCR6 axis." (PMID 35869057, 2022). "CXCR6-dependent Recruitment of NKT cells and CD4+ T cells to the liver exerts important functions in tumor surveillance to inhibit hepatocarcinogenesis." (PMID 34983554, 2022). "At day 2 post-transfer, Ox/Cy enhanced accumulation of CAR-T cells in tumors excised from KPROR1 mice, and this accumulation was partially CXCR6-dependent, as CXCR6−/− CAR-T cells showed poorer tumor infiltration compared to their wild type counterparts." (PMID 36311728, 2022). "ORFV infection induces tumor cell apoptosis that facilitates phagocytosis of dying tumor cells by DCs and recruits CD8 T cells through the CXCL16/CXCR6 axis." (PMID 35959371, 2022). "Bone-homing tumor cells tend to overexpress chemokine receptors, CXCR4, CXCR6, and CXCR2 that subsequently contribute to the movement of the tumor cells from the bone marrow to other organs by seeking CXCL12, CXCL-16, and CXCL-10 respectively." (PMID 35399952, 2022). "Since CXCR6 is the receptor that chemoattracts TEff/EM cells in the tumor, we predicted that its sole ligand, CXCL16, would be expressed in the tumor tissue." (PMID 33979626, 2021). "It has also been demonstrated that CXCL16/CXCR6 signaling acts directly on the primary GBM cells, promoting tumor cell growth, migration, and invasion." (PMID 34071306, 2021). "This triggers the migration of anti-tumor TILs into the tumor, in particular, activated CD8+CXCR6+ T cells and activated NK cells." (PMID 33800554, 2021). "When given prophylactically, anti-PD1 treatment led to an increase in the incidence of NASH–HCC and in the number and size of tumour nodules, which correlated with increased hepatic CD8+PD1+CXCR6+, TOX+, and TNF+ T cells." (PMID 33762733, 2021). "In contrast to MAV-affected WT mice which successfully controlled tumor growth, tumors in MAV-affected CXCR6−/− mice had similar growth kinetics to those of unaffected or naïve mice." (PMID 34362825, 2021). "The CXCL16/CXCR6 signaling axis has been reported involved in several kinds of tumor and in multiple signaling pathways in malignant cells, suggesting that CXCL16/CXCR6 axis is a critical role in tumor tumorigenesis and progression 12-14." (PMID 34345211, 2021). "The interaction between CXCR6-expressing TRM cells and CXCL16-expressing APCs was found to be critical for sustaining TRM cell–mediated tumor protection." (PMID 34362825, 2021). "A larger tumor enhanced CEA concentration and a higher TNM stage enhanced CXCR6 expression were correlated with worse overall survival rates." (PMID 33182840, 2020). "Biological significance of CXCR6 and CXCL16 was tested using tumor cell migration and invasion assays." (PMID 30792527, 2019). "This study examined the co-stimulatory role of CXCR6/CXCL16 interactions in glycolipid-dependent iNKT cell activation and tumor control." (PMID 27471636, 2016).
tumor (continued). "In this study, we have demonstrated that co-stimulatory CXCR6/CXCL16 interactions specifically increase IFNγ production following glycolipid activation and lead to enhanced tumor control in vivo following adoptive DC transfer." (PMID 27471636, 2016). "These experiments implicate an important role for CXCR6/CXCL16 interactions in regulating iNKT cell IFNγ production and tumor control." (PMID 27471636, 2016). "In conclusion, our data demonstrate that CXCR6/CXCL16 co-stimulatory interactions between DCs and iNKT cells play an important role in mediating glycolipid-dependent tumor control." (PMID 27471636, 2016). "Both CXCR6−/− and CXCL16−/− mice exhibit enhanced tumor growth and metastasis in experimental models." (PMID 27471636, 2016). "With respect to the CXCL16/CXCR6 axis, we were the first to report that CXCL16 expression by tumor cells enhances the recruitment of tumor-infiltrating lymphocytes, thereby bringing about a better prognosis for CRC patients." (PMID 25495942, 2014). "Like IGR39 cells sorted based on CXCR6 expression alone, tumors from IGR39 ABCG2+/CXCR6+ cells required only 21 days for tumor detection." (PMID 21203549, 2010). "Mechanistically, a circuit of bile acid, CXCL16, CXCR6, and NKT cell links gut microbes to hepatic anti-tumor surveillance: microbial 7α-dehydroxylation of bile acids lowers sinusoidal CXCL16, reduces CXCR6+ NKT cell accumulation, and favors hepatocarcinogenesis." (PMID 41486167, 2026). "Notably, CXCR6 suppression also led to diminished expression of key PI3K–AKT pathway elements, along with reduced tumor-killing function." (PMID 41565617, 2026). "Furthermore, PTT's thermal effects increase tumor vascular permeability and perfusion, facilitating immune cell infiltration and CXCR6+ and CCR7+ T‐cell recruitment, which collectively drive potent anti‐tumor immunity." (PMID 41298282, 2026). "In functional assays with peripheral blood from five untreated patients and ten LEN-TAP–responsive patients (five used for CXCR6 knockdown), coculture for 72 h revealed that LEN-TAP treatment increased tumor-cell BAD expression; CXCR6 silencing attenuated this effect." (PMID 41565617, 2026). "Additionally, azvudine regulated the interactions from other tumor immune cells to CD4+ T and CD8+ T cells through ligand‒receptor pairs such as COL1A2‒(ITGA1 + ITGB1), CCL4‒CCR5, CCL6‒CCR2, and CXCL16‒CXCR6." (PMID 39819859, 2025). "Recent studies show that low-dose radiotherapy (LDRT) combined with PD-1 inhibitors can induce stem-like CD8+ T cells from tumor-draining lymph nodes (TDLN) to the tumor and differentiate into CXCR6+ effector subpopulations, generating an abscopal effect, and forming long-term immune surveillance." (PMID 41415276, 2025). "Consistent with this, the primary ligands for CXCR3, CCR5 and CXCR6 correlated with T-cell- and macrophage-specific genes, but not with tumor cells, B cells or fibroblasts." (PMID 41415437, 2025). "CXCL16 is a ligand for CXCR6, which is preferentially expressed on tumor-infiltrating CD8+ T cells but absent on peripheral CD8+ T cells." (PMID 40148310, 2025). "Although its corresponding receptor CXCR6 was not differentially expressed, the CXCL16–CXCR6 pair exhibited a positive spatial correlation, suggesting potential coordination between tumor cells and neighboring Tregs." (PMID 40776410, 2025). "Importantly, engineering CAR-T cells to express CXCR6 or RUNX3 enhances their intratumoral persistence and tumor control, highlighting the translational potential of modulating this pathway." (PMID 41479900, 2025). "Together, these studies indicate that local CXCL16 expression in tissues by stromal or tumor cells plays a critical role in TRM attraction and residency via CXCR6 and may compete to dictate where TRM precursors localize." (PMID 40862776, 2025).
tumor (continued). "In NSCLC, activation of tissue-resident NK cells were reported to have an exhausted phenotype (CD69 + CXCR6+), highlighting their noncytotoxic function resulting in poor anti-tumor immunity." (PMID 40849493, 2025). "Moreover, macrophages and DC1 cells within the tumor microenvironment secreted CXCL16, which recruited CXCR6+ CD8+ T cells and CXCR6+ NK cells to bolster anti-tumor responses." (PMID 39588301, 2024). "An elevated percentage of tumor-infiltrating CXCR6+CD8+MAIT cells was observed (18 responders and 14 non-responders; 47.44% VS 26.72%, P = 0.0274)." (PMID 38698468, 2024). "While a genome-wide association study identified a positive correlation between LCL CXCL16 expression and EBV copy number, it is not known if CXCR6 is required for the effective trafficking of VST to EBV PTLD tumor sites." (PMID 39011042, 2024). "In RCC, the expression of CXCL16 and its cognate receptor CXCR6 also associates with better survival outcomes in patients; however, neither has been linked with VHL loss or tumor-infiltrating lymphocyte (TIL) infiltration." (PMID 38618956, 2024). "However, CXCR6 is also important in anti-tumor immunity, highlighting a complex relationship between TCF1, CXCR6 and T cell function." (PMID 39749327, 2024). "Although the CXCR6-mediated retention of TRM cells is required for inhibition of tumor progression, how TRM cells block tumor metastasis remains unclear." (PMID 39193473, 2024). "The reason why there seems to be an overall reduction in TAMC infiltration as well as T-cell infiltration in CXCR6 KO tumor-bearing mice is not clear." (PMID 38299146, 2023). "Tumor cells with fused genes showed overexpression of FOSB, FOS, and JUN, while tumor cells without fused genes overexpressed CXCR6 and DUSP4." (PMID 37736898, 2023). "In HCC, MAIT cells are greatly reduced in tumors compared to adjacent tissues, which may be attributed to the downregulation of CCR6, CXCR6, and CCR9 on tumor-educated MAIT cells." (PMID 36773210, 2023). "Expression of CXCR3, CXCR6, CCR2, and CCR5 differed between trNK cells, ILCs, CD8+ TRM cells, and CD4+ TRM cells, as well as between locations within the tumor and tumor-distal lung tissue." (PMID 37448786, 2023). "We further found that CXCL16 was highly expressed in Macro_APOE/CTSZ and CXCR6 was expressed in Treg, which might indicate that Macro_APOE/CTSZ utilized CXCL16 signals to recruit Treg cells to the tumor site, further exacerbating the immunosuppressive TME." (PMID 36587392, 2023). "These elegant works on the role of CXCR6 in T cell differentiation focusing on anti-tumor T cells, do not specify its impact on the differentiation of exhausted T cells and TRM." (PMID 36311728, 2022). "Because the RNA expression profile of NK cells expressing PD-1 and CXCR6 suggested that they may be connected, we compared the expression of PD-1 on CXCR6 and CD62L subsets of tumor infiltrating NK cells in the MTAP1A tumor model by flow cytometry." (PMID 36185379, 2022). "Ten chemokine receptors (CXCR1, CXCR2, CXCR4, CXCR6, CCR3, CCR6, ACKR4/CCRL1, CCLR2, CX3CR1, and ACKR1/DARC) were identified as differentially expressed from the DEG analysis between Black, White and Asian patient normal and tumor samples." (PMID 35754051, 2022). "Additionally, CXCR6 surface expression on mouse and human lung TRM cells upon tumor antigen encounter facilitates their migration and maintenance in lung TME." (PMID 36305904, 2022). "Phenotypic and functional characterization of tumor-infiltrating ILC1s revealed a decrease in CXCR6+ ILC1s and an increase in CD49a+ ILC1s within tumor compared to nontumor tissue and healthy controls." (PMID 35962192, 2022). "In terms of mechanism, CXCR6 was not essential for extravasation of blood-borne CD8+ T cells into tumor tissue." (PMID 36311728, 2022).